CSN1S1 (casein alpha s1)
Description:
Important role in the capacity of milk to transport calcium phosphate. Casoxin D acts as opioid antagonist and has vasorelaxing activity mediated by bradykinin B1 receptors.
Synonyms: CASA; CSN1
Tractability: Antibody: its Gene Ontology location is reachable by antibodies, with high confidence; UniProt places it where antibodies can reach, with medium confidence; UniProt predicts a signal peptide or a membrane-spanning region.
Gene: Protein-coding gene on chromosome 4 (69,931,068 to 69,946,574, forward strand). Ensembl gene ENSG00000126545.
Subcellular location: Secreted
Pathways (Reactome):
Transport of small molecules: Miscellaneous transport and binding events
Gene Ontology:
Molecular function: protein binding
Biological process: response to 11-deoxycorticosterone; response to dehydroepiandrosterone; response to estradiol; response to progesterone
Cellular component: extracellular region
Genetic constraint (gnomAD): Loss-of-function variants: 17 observed, 13.37 expected, observed/expected ratio (o/e) 1.27, 90% interval 0.87 to 1.82. The upper end of that interval is the gene's LOEUF score, 1.82, which puts it in group 6 of 6, group 1 being the genes least tolerant of losing a copy. Missense variants: 117 observed, 94.17 expected, observed/expected ratio (o/e) 1.24, 90% interval 1.07 to 1.45. Synonymous variants: 41 observed, 33.24 expected, observed/expected ratio (o/e) 1.23, 90% interval 0.96 to 1.6.
Homologues: Orthologues: chimpanzee CSN1S1 (97% identical), macaque CSN1S1 (84% identical), dog CSN1S1 (54% identical), pig CSN1S1 (48% identical), mouse Csn1s1 (38% identical).
Diseases named in the same sentence as CSN1S1 in open-access papers:
CSN1S1 is named in the same sentence as 29 diseases in open-access papers, as found by Europe PMC text mining. Sharing a sentence is not in itself a finding about the gene and the disease. The quoted sentences say what the papers report.
mastitis (7 papers, 2009 to 2023). Inflammation of breast tissue during lactation or postpartum due to an obstructed duct or infection. "Principally, DNA-remethylation around the STAT5-binding enhancer in the CSN1S1 promoter was shown to be associated with shutdown of αS1-casein synthesis during acute mastitis." (PMID 19508288, 2009). "The effect of clinical mastitis on methylation patterns has been demonstrated in the case of DNA remethylation around the STAT5-binding enhancer in the CSN1S1 promoter leading to disruption of αS1-casein synthesis during intramammary infection." (PMID 36759924, 2023). "Research has found that subclinical mastitis affected protein composition of milk, and LPS-induced mastitis affected the expression of milk protein genes (Csn1s1 and Csn2)." (PMID 33505589, 2021). "CSN1S1 gene expression had previously been linked to the methylation profile of a distal upstream region of the CSN1S1 gene after mastitis." (PMID 25369064, 2014). "Furthermore, inflammation induced by mastitis has been shown to reduce CSN1S1 expression and increase the DNA methylation of three CpG located within a distal upstream regulatory region of the gene." (PMID 25369064, 2014). "The CSN1S1 gene has been reported to be epigenetically regulated during mastitis." (PMID 19508288, 2009). "The decrease in milk production during mastitis in dairy cows is due to pathogens (such as S. aureus and Escherichia coli) that induce hypoxia, oxidative stress, and apoptosis, while suppressing the expression of milk genes (Csn2, Lalba, and Csn1s1) in the mammary gland." (PMID 35795861, 2022). "This is a low methylation level, when compared with that in the liver which does not express the CSN1S1 gene, and it is interesting to note that the methylation level of this region increases in a context of ODM and mastitis when CSN1S1 expression decreased." (PMID 25369064, 2014).
breast carcinoma (3 papers, 2021 to 2025). "While these genes primarily function in lactation, a previous study using TCGA breast cancer datasets reported lower CSN1S1 expression in breast cancer tissues compared to healthy breast tissue, and this lower expression is associated with better prognosis." (PMID 40986521, 2025).
allergies (2 papers, 2016 to 2021). "On the other hand, BLG and CSN1S1 are the potential allergens for some peoples, therefore, milk production with few amount of these proteins might be used for people with allergies to these milk proteins." (PMID 28959346, 2016).
multiple sclerosis (2 papers, 2013 to 2024). A progressive autoimmune disorder affecting the central nervous system resulting in demyelination. "More recently, a member of the casein family, casein alpha s1 (CSN1S1), was shown to be expressed outside the mammary gland: overexpression was noted in lymph nodes of encephalomyelitic mice and blood of multiple sclerosis patients." (PMID 24083466, 2013). "Recently, CSN1S1 expression was found in the lymph nodes and blood of multiple sclerosis patients." (PMID 39590217, 2024). "The recent findings of CSN1S1 overexpression in the autoimmune diseases multiple sclerosis and rheumatoid arthritis may be considered supportive of this hypothesis." (PMID 24083466, 2013).
benign prostate hyperplasia (1 paper, 2021). "Because of significantly different protein expression in benign prostate hyperplasia compared with normal and tumor prostate tissues, CSN1S1 has been reported as a potential biomarker for early identification of benign prostate hyperplasia patients." (PMID 33462316, 2021).
breast tumor (1 paper, 2021). "Moreover, CSN1S1 has identified as a tumor suppressor that controls breast tumor growth and metastasis." (PMID 33462316, 2021).
food allergy (1 paper, 2022). Gastrointestinal disturbances, skin eruptions, or shock due to allergic reactions to allergens in food. "αS1-Casein (encoded by the CSN1S1 gene) is associated with food allergy more than other milk protein components." (PMID 35159497, 2022).
Hypertension (1 paper, 2024). The presence of chronic increased pressure in the systemic arterial system. "Notably, neurogranin (NRGN) levels were significantly associated with hypertension and smoking, while casein alpha S1 (CSN1S1) levels varied with statin use." (PMID 39590217, 2024).
Obesity (1 paper, 2020). Accumulation of substantial excess body fat. "Importantly, we identified four genes (CSN1S1, DMRT2, DMRT3 and HOXA5) as novel candidate genes of body fat distribution pattern in Africans, whose biological function and implication in the pathogenesis of obesity-associated metabolic diseases remain to be unravelled." (PMID 32581226, 2020).
tumor (5 papers, 2009 to 2021). "Neu tumor cells can be divided into Cluster 1 and Cluster 2, both expressing higher levels of genes associated with secretory alveolar differentiation such as Csn1s1, Lalba and Tspan8." (PMID 32840210, 2020). "According to our finding, GATA3-mutants had larger tumor size that it may be due to the down-regulation of CSN1S1." (PMID 33462316, 2021). "We constructed a novel seven-gene signature (B3GALT5-AS1, DNER, CSN1S1, KIF5A, SIX3, NOTUM, and CPS1) and a combined prognostic model integrating a seven-gene signature with patient age and tumor size to quantify the likelihood of distant metastasis in lymph node-negative TNBC." (PMID 34604089, 2021).
cancer (2 papers, 2021 to 2023). A tumor composed of atypical neoplastic, often pleomorphic cells that invade other tissues. "The significantly overexpressed sEV proteins in the BC plasma-derived UCT isolates were ALB, COL1A1, CSN1S1, EEF1A2, and RPL3; and the C1S, C5, C7, and CFHR2 sEV proteins in the UCT isolates were the most downregulated proteins in the BC plasma compared to the non-cancer control." (PMID 37895140, 2023).
CSN1S1 also shares sentences with these, for which no sentence is quoted: asthenospermia (2 papers); abscess (1); Anxiety (1); autoimmune disease (1); Bovine mastitis (1); cortical cataract (1); COVID-19 (1); depression (1); E. coli infection (1); Hepatic steatosis (1); infection (1); lung carcinoma (1); metabolic disease (1); oligospermia (1); posterior subcapsular cataract (1); prion disease (1); rheumatoid arthritis (1); viral infections (1).